PFKP (phosphofructokinase, platelet)
Diseases named in the same sentence as PFKP in open-access papers (continued):
Sharing a sentence is not in itself a finding about the gene and the disease.
breast cancer (continued). "However, PubMed text mining showed there were only four publications focused on PFKP in reference to breast cancer." (PMID 31231467, 2019). "Hence, PFKP plays a key role in regulating Snail-mediated metabolic reprogramming in breast cancer cells." (PMID 28176759, 2017). "Moreover, PFKP could also be involved in cell invasion and metastasis in breast cancer and oral squamous cell carcinoma." (PMID 37833332, 2023). "In addition, PFKP can be used as a therapeutic target in patients with breast cancer." (PMID 36339718, 2022). "PFKP has been found to be overexpressed in a variety of cancers, including breast cancer (BC) and glioblastoma (GBM)." (PMID 36276846, 2022). "Interestingly, knockdown of PFKP in breast cancer cells induced dormancy-like cell cycle arrest with gain of resistance against oxidative stress, such as glucose starvation or paclitaxel treatment, indicating the importance of flux control between glycolysis and PPP." (PMID 32927665, 2020). "Therefore, maybe there are functional connections between BRCA1, PPARγ and PFKP in glycolysis system and PFKP inhibitor may have a potential effect on BRCA1 dysfunctional breast cancer patients who suffer from diabetes and need treatments with PPARγ agonists." (PMID 32470015, 2020). "Here we show that phosphofructokinase platelet (PFKP), a key glycolytic enzyme, is highly expressed in breast cancer." (PMID 42024199, 2026). "In breast cancer, KLF4 contributes to the maintenance of high glycolytic metabolism through the transcriptional activation of the PFKP gene, which further supports breast cancer progression." (PMID 40616161, 2025). "A dietary polyphenolic compound, quercetin, suppressed growth and migration by inhibiting PFKP and LDHA expression in breast cancer." (PMID 37151384, 2023). "Regarding its commitment to tumor metabolic rewiring, in breast cancer, elevated KLF4 expression has been detected and contributes to activating phosphofructokinase (PFKP), a key enzyme involved in the glycolysis pathway." (PMID 37835497, 2023). "Simultaneous overexpression of PFKP and LDHA has previously been described in a breast cancer cell line (MDA‐MB‐231), in which PFKP regulation also affects lactate production." (PMID 37326348, 2023). "The results revealed that depletion of Zeb1 inhibited the expression and activity of HK2, PFKP and PKM2; however, ectopic Zeb1 expression had the opposite effect to enhance the glycolytic phenotypes in breast cancer cells." (PMID 35246504, 2022). "Further study showed that HRD1 catalyzed PFKP ubiquitination and promoted PFKP degradation, indicating a potential involvement of HRD1 in aerobic glycolysis in breast cancer cells." (PMID 33588886, 2021). "Nevertheless, quercetin impaired the PFKP-LDHA signaling axis, and thus inhibited the migration of breast cancer (MDA-MB-231) cells induced by aerobic glycolysis." (PMID 33401572, 2021). "As PFKP was regulated by BRCA1/ZBRK1 axis, we next explored what the role of PFKP in cell growth and colony formation in breast cancer cells MDA-MB-231." (PMID 32470015, 2020). "To further verify the regulatory function of ZBRK1 on PFKP, we knocked down ZBRK1 in breast cancer cell line MCF-7 and performed Western blotting and real time PCR assay." (PMID 32470015, 2020). "The down-regulation of PFKP, a key glycolytic enzyme, by WNT5A signaling correlates with the ability of WNT5A to decrease lactate secretion in breast cancer cells." (PMID 29069720, 2017). "Using Western blotting, we investigated the expression of HK, PK and PFKP in MDAMB-468-5A cells, as these glycolytic enzymes are crucially involved in the production of lactate and play essential roles in breast cancer progression." (PMID 29069720, 2017). "To examine the role of PFKP in regulating glucose flux between glycolysis and PPP, we next determined NADPH and ROS levels in breast cancer cells according to the PFKP abundance." (PMID 28176759, 2017).
breast cancer (continued). "Using a combination of these markers, 60 HR+/HER2+ breast cancer patients were classified into the following subtypes: (a) IHC-III: CD8A+; (b) IHC-IV: CD8A− and KRT5+; (c) IHC-II: CD8A−, KRT5− and GFRA1+; (d) IHC-I: CD8A−, KRT5−, GFRA1− and PFKP+." (PMID 40133264, 2025). "They found that in breast cancer, KLF4 could upregulate the expression of PFKP by directly binding to the PFKP promoter." (PMID 37833332, 2023). "Here, we show that ectopic Zeb1 directly increases the transcriptional expression of HK2, PFKP, and PKM2, which are glycolytic rate-determining enzymes, thus promoting the Warburg effect and breast cancer proliferation, migration, and chemoresistance in vitro and in vivo." (PMID 35246504, 2022). "Interestingly, clustering analysis with PFKP and FBP1 revealed distinct breast cancer subtypes, and transcript abundance of the two genes were inversely correlated." (PMID 32927665, 2020). "The paradoxical suppression of PFKP and FBP1 by Snail suggested molecular subsets of different catabolic metabolism in breast cancer, leading us to further investigate metabolic-dependency based on breast cancer subtypes." (PMID 32927665, 2020). "Interestingly, PFKP and FBP1 are inversely correlated in clinical samples, indicating different metabolic subsets of breast cancer." (PMID 32927665, 2020). "Similarly, SNAI1 also represses phosphofructokinase platelet (PFKP) and several subunits of cytochrome C oxidase (COX) in breast cancer cells, further reinforcing a strongly glycolytic metabolic phenotype." (PMID 31277295, 2019). "Therefore, it can be inferred that USP5 influences breast cancer progression by targeting either the HIF protein or the PFKP protein, which in turn may directly or indirectly impact the function of PFKP." (PMID 38217030, 2024). "In breast cancer, PFKP, but not PFKM or PFKL, correlates with malignant features and poor survival." (PMID 37444501, 2023). "Since Zeb1 regulates expression of the glycolytic rate-determining enzymes HK2, PFKP and PKM2 that modulate cancer cell proliferation and/or apoptosis, the function of Zeb1 in aerobic glycolysis at least partly explains the phenotypes induced by Zeb1 depletion in breast cancer cells." (PMID 35246504, 2022). "Because we have shown that WNT5A inhibits PFKP expression in breast cancer cells and that PFKP directly regulates aerobic glycolysis, migration and invasion of breast cancer cells, we investigated the mechanism of WNT5A-mediated regulation of PFKP expression in breast cancer cells." (PMID 29069720, 2017). "However, the glycogen level was not increased by PFKP silencing regardless of glucose concentration in breast cancer cells." (PMID 28176759, 2017). "Interestingly, PFKP abundance did not affect the transcript abundance of EMT genes which were regulated by Snail in breast cancer cells, indicating that the Snail-PFKP axis mainly involves glucose metabolism independent of phenotypic conversion." (PMID 28176759, 2017). "At the present study, we analyzed by CellMiner that the expression level of PFKP was positively related to the drug activity of protein kinase C (PKC) inhibitor Staurosporine, suggesting that the expression level of PFKP could affect the drug sensitivity of breast cancer cells to PKC inhibitors." (PMID 32470015, 2020). "The clinical significance of HRD-mediated degradation and decreased stability of PFKP was also indicated by the negative correlation between HRD and PFKP expression in human breast cancer tissues." (PMID 33588886, 2021).
lung carcinoma (29 papers, 2018 to 2025). "One study silenced PFKP expression causing cell cycle arrest at the G2/M phase, which significantly suppressed colony formation and proliferation of lung cancer cells." (PMID 37151384, 2023). "Phosphofructokinase platelet (PFKP) is a gene encoding a rate-limiting enzyme of glycolysis, and its role in mediating glycolytic regulation of tumor progression has been well-established in lung cancer and advanced prostate cancer." (PMID 40134432, 2025). "A recent research work has shown that D-fructose 6-phosphate associated with PFKP may be a prognostic factor for lung cancer." (PMID 34690780, 2021). "Functional studies confirmed that reducing PFKP expression in lung cancer cells decreased glucose uptake, lactate production, and cell proliferation, highlighting its role in tumour metabolism and growth." (PMID 41154605, 2025). "PFKP was significantly overexpressed in lung cancer tissues as confirmed via IHC staining, which correlated with larger tumour size and poorer patient prognosis." (PMID 41154605, 2025). "In lung cancer cell lines with decreased PFKP expression, the glucose uptake rate, lactate level, and adenosine triphosphate concentration are significantly reduced." (PMID 38965505, 2024). "Multiple studies have demonstrated that ABCC2 and PFKP play a carcinogenic role in the development of lung cancer." (PMID 39148731, 2024). "SPFKP was found to affect cell stemness of HCC cells, whereas in lung cancer, PFKP was found to regulate glucose metabolism." (PMID 38233508, 2024). "To explore the biological function of PFKP on lung cancer cells in vitro, we knocked down PFKP using siRNAs and verified its knockdown efficiency by Western blot." (PMID 39664584, 2024). "For instance, studies have shown that PFKP is highly expressed in lung cancer tissues, and its silencing resulted in a significant reduction in cell growth, and impaired colony-forming ability." (PMID 38982480, 2024). "In this study, we found that the PFKP expression level was higher in lung cancer and correlated with unfavorable survival." (PMID 39664584, 2024). "The cell colony formations were significantly increased upon ectopic PFKP overexpression in lung cancer cell lines." (PMID 39664584, 2024). "The results showed that the PFKP protein was highly expressed in lung adenocarcinomas, and higher expression of the PFKP protein was related to poor patient survival in lung cancer." (PMID 39664584, 2024). "To determine if PFKP is important in human lung cancer progression, we performed PFKP protein expression and KEGG pathway analysis based on human lung specimens." (PMID 39664584, 2024). "Subsequently, the impact of NPs-mediated PFKP silencing on lung cancer growth was evaluated using a mouse xenograft model." (PMID 39664584, 2024). "Though the biological functions of PFKP in lung cancer have been elucidated, the mechanism of its relationship with specific oncogenic pathways is not fully understood." (PMID 39664584, 2024). "Research and analysis have shown that PFKP is highly expressed in lung cancer tissues and cell lines and that its high expression is associated with poor prognosis." (PMID 38965505, 2024). "In conclusion, PFKP is highly expressed in lung cancer and significantly contributes to poor patient survival." (PMID 39664584, 2024). "In lung cancer cells, PFKP knockdown significantly decreased the glucose uptake rate and ATP production." (PMID 37151384, 2023). "For example, PFKP is highly expressed in lung cancer and regulates cell proliferation by regulating glycolytic activity." (PMID 37833332, 2023). "For example, PFKP expression levels are negatively correlated with the prognosis of lung cancer, and the proliferation rate of cells with low PFKP expression is significantly reduced." (PMID 36339718, 2022). "Namely, PFKP is lowly expressed in seminomas and embryonal carcinomas but highly expressed in human breast tumor cells and lung cancer." (PMID 34595103, 2021).
lung carcinoma (continued). "Recent studies showed that PFKP is highly expressed in lung cancer and promotes lung cancer development via fructose and mannose metabolism." (PMID 33344071, 2020). "This is in agreement with a previous study that also reported PFKP to be downregulated in PCa, but in contrast to lung cancer where PFKP has been suggested as an oncogene." (PMID 30866497, 2019). "In addition, the knockdown of PFKP impaired cell proliferation, migration, invasion, and colony formation in lung cancer indicating that PFKP plays an oncogenic role in lung cancer." (PMID 39664584, 2024). "Indeed, we observed that GS markedly enhanced p-ACC level in the mitochondrial fraction in various lung cancer cell lines, and such changes were found to be PFKP-dependent." (PMID 35641476, 2022). "PFKP, involved in metabolism, is a suggested oncogene in lung cancer." (PMID 36551208, 2022). "PFKP is up-regulated in lung cancer and regulates glucose metabolism." (PMID 33839701, 2021). "PFKP, PGAM1 and PGK1 are key metabolic enzymes in lung cancer, contributing to tumour progression and patient prognosis." (PMID 41154605, 2025). "To further investigate the role of PFKP in TME, we constructed Lewis lung cancer model in C57BL/6 mice (LLC group, LLC group with radiation, LLC group with radiation and PD-1 antibodies)." (PMID 38977778, 2024). "The correlation of the four genes HMMR, PFKP, TCN1, and TK1 with tumor-infiltrating immune cells and the survival curve in lung cancer was shown." (PMID 35898471, 2022). "PFKP plays critical roles in not only metabolic processes but also in non-metabolic pathways for lung cancer progression." (PMID 39664584, 2024). "The role of PFKP-mediated c-Myc expression in HNSCC progression, growth, angiogenesis, and metastasis was further analyzed using a subcutaneous xenograft tumor model in vivo, a CAM assay, and a tail vein lung cancer metastasis mouse model." (PMID 38982480, 2024). "Beyond its known role in glycolysis, PFKP also has a non-metabolic function in affecting lung cancer progression by interacting with the AXL-MET axis, thus indicating a potential therapeutic target for lung cancer." (PMID 39664584, 2024). "PFKP and SLC7A11 have been reported to regulate the metabolic levels of lung cancer cells." (PMID 33042838, 2020). "To further understand the potentially significant role of PFKP in lung cancer progression, we performed proteomics and genomic analysis using DIA-MS technology and RNA sequencing following PFKP knockdown with siRNAs in H838, H1299, and A549 lung cancer cell lines." (PMID 39664584, 2024). "PFKP plays critical roles in metabolic and non-metabolic pathways for lung cancer progression." (PMID 39664584, 2024).
glioblastoma (17 papers, 2019 to 2025). The most malignant astrocytic tumor (WHO grade IV). "Increases in HKs and PFKP have been associated with increased growth, aggression, and proliferation in many tumors, including glioblastoma." (PMID 41473749, 2025). "In glioblastomas, PFKP S386 phosphorylation prevents the TRIM21-mediated ubiquitylation and degradation of PFKP, leading to an increase in aerobic glycolysis." (PMID 33588886, 2021). "However, other ubiquitin ligases, TRIM21 and A20, have been reported to catalyse ubiquitination-mediated degradation of PFKP in glioblastoma and PFKL in hepatocellular carcinoma." (PMID 35670764, 2022). "Furthermore, PFKP has been reported to enhance the nuclear translocation and activation of β-catenin, further augmenting the expression of its downstream gene, c-Myc, in human glioblastoma cells." (PMID 38982480, 2024). "Moreover, stabilization of PFKP in human glioblastoma is involved in tumorigenesis." (PMID 37833332, 2023). "PFKP phosphorylation is required for AKT-mediated β-catenin S552 phosphorylation and subsequent β-catenin transactivation in human glioblastoma cells." (PMID 40612109, 2025). "In human glioblastoma cells, PKF1 platelet isoform (PFKP) is the major isoform of PFK1 and functions as a key signaling molecule on the plasma membrane that regulates PI3K/Akt activation." (PMID 40612109, 2025). "PFKP induced PD-L1 expression through EGFR activation and promoted immune evasion in human glioblastoma cells." (PMID 37622118, 2023). "Glioblastoma (GBM) is a highly vascular malignant brain tumor that overexpresses vascular endothelial growth factor (VEGF) and phosphofructokinase 1 platelet isoform (PFKP), which catalyzes a rate-limiting reaction in glycolysis." (PMID 36435833, 2022). "PFKP has been reported to contribute to metabolic reprogramming and maintain cell proliferation in clear cell renal carcinoma, and promote tumorigenesis in glioblastoma, but has not been well studied in HCC." (PMID 31847435, 2019).
leukemia (14 papers, 2021 to 2025). A malignant (clonal) hematologic disorder, involving hematopoietic stem cells and characterized by the presence of primitive or atypical myeloid or lymphoid cells in the bone marrow and the blood. "In a study where R-2HG was shown to attenuate aerobic glycolysis in leukemia by targeting the FTO/m6A/PFKP/LDHB axis, it was found that PFKP promotes glycolysis and exerts an oncogenic role in leukemia." (PMID 39820532, 2025). "The FTO/PFKP/LDHB axis has been shown to be involved in glycolysis in leukemia via m6A modification." (PMID 41373022, 2025). "Recent study revealed that the increased expression of phosphofructokinase platelet (PFKP) is tightly connected with metabolic activities to reduce the chemotherapy sensitivity in leukemia initiating cells (LICs)." (PMID 39025844, 2024). "On the other hand, 2-HG attenuates aerobic glycolysis in leukemia by targeting the FTO/m6A/PFKP/LDHB axis." (PMID 34516556, 2021). "Additionally, one study revealed that R-2HG attenuated aerobic glycolysis in leukemia by targeting the FTO/m6A/PFKP/LDHB axis." (PMID 41373022, 2025). "In leukemia, PFKP affected disease progression by influencing CXCR4-dependent T-cell infiltration." (PMID 38233508, 2024). "Moreover, a recent study found that R-2HG also suppresses glycolysis in leukemia cells by abrogating FTO/m6A/YTHDF2-mediated upregulation of two critical glycolytic genes phosphofructokinase platelet (PFKP) and lactate dehydrogenase B (LDHB)." (PMID 34485297, 2021). "For instance, YTHDF2 accelerates decay of GLUT4 mRNA in BRCA,253 while facilitates expression of PFKP and LDHB in leukemia, leading to opposite effects." (PMID 38531882, 2024). "In R-2HG-sensitive leukemia cells, R-2HG suppresses FTO activity and decreases the stability of target mRNA phosphofructokinase platelet (PFKP) and lactate dehydrogenase B (LDHB) by YTHDF2." (PMID 35864970, 2022). "R-2HG can block the post-transcriptional upregulation of PFKP and LDHB mediated by FTO/m6A, thus attenuating aerobic glycolysis in sensitive(IDH-wildtype) leukemic cells and inhibiting the occurrence of leukemia." (PMID 35590394, 2022). "In addition, the FTO/m6A/PFKP/LDHB axis is targeted by R-2-hydroxyglutarate, resulting in the suppression of aerobic glycolysis in leukemia." (PMID 37858219, 2023). "Scholars have reported that R-2-hydroxyglutarate (R-2HG) abates FTO/m6A/YTHDF2-mediated upregulation of phosphofructokinase platelet (PFKP) and lactate dehydrogenase B (LDHB) which suppress aerobic glycolysis and exert an anti-tumor effect in R-2HG-sensitive leukemia cells." (PMID 36035161, 2022). "PFKP and LDHB play an important role in glycolysis and tumorigenesis of leukemia." (PMID 35590394, 2022).